ALKBH5 (alkB homolog 5, RNA demethylase)
Diseases named in the same sentence as ALKBH5 in open-access papers (continued):
Sharing a sentence is not in itself a finding about the gene and the disease.
bladder cancer (39 papers, 2019 to 2025). "One research team has reported that ALKBH5 exerted an inhibitory effect on bladder cancer by disrupting the glycolytic process in bladder cancer cells." (PMID 40001461, 2025). "Subsequently, through univariate Cox regression analysis, we identified ALKBH5, FTO, IGF2BP2, and IGF2BP3 as potential risk factors for bladder cancer." (PMID 40083693, 2025). "Mechanistically, ALKBH5 impeded the progression of bladder cancer and enhanced the sensitivity of bladder cancer cells to cisplatin by modulating the glycolysis pathway through CK2α in an m6A-dependent manner." (PMID 40001461, 2025). "The differential dependency of FTO and ALKBH5 in the same tumor context has also been reported in bladder cancer and B cell lymphoma." (PMID 40435251, 2025). "Expanding on our understanding of bladder cancer, ALKBH5 expression was found to be significantly downregulated, and its low expression is associated with poor prognosis in patients." (PMID 39759516, 2024). "Previous studies have found that the methyltransferase METTL3 and demethylase ALKBH5 are aberrantly expressed in bladder cancer cells and are involved in the development of bladder cancer." (PMID 38267663, 2024). "For instance, it is demonstrated that ALKBH5 is downregulated in bladder cancer cells and predicts poor prognosis of bladder cancer individuals." (PMID 37055798, 2023). "Silencing ALKBH5 enhances the proliferation, migration, and invasion of bladder cancer cells and reduces their chemosensitivity to cisplatin via the CK2α-associated glycolytic pathway." (PMID 37007161, 2023). "In bladder cancer, it has demonstrated that ALKBH5, IGFBP2-3, RBM15, RBMX, YTHDC1, and YTHDF had prognostic value." (PMID 37701836, 2023). "ALKBH5 can reduce the stability of CK2α mRNA in a m6A-dependent manner, significantly inhibiting the proliferation of bladder cancer cells and sensitizing bladder cancer cells to cisplatin in vivo and in vitro." (PMID 35945641, 2022). "We found that a low expression of METTL14 (a m6A methyltransferase), SMPD4, and SGK2, but a high expression of ALKBH5 (a m6A de methyltransferase), LINC00482, and HIPK3, showed a tendency to associate with worse overall survival in bladder cancer patients." (PMID 34868913, 2021). "Recently, studies also reported that ALKBH5 suppressed bladder cancer cell proliferation and induced sensitivity to cisplatin-based chemotherapy through m6A-CK2a-mediated glycolysis." (PMID 35004726, 2021). "explored that m6A writer METTL3 and eraser ALKBH5 regulator cell adhesion via embellishing ITGA6 expression in bladder cancer." (PMID 34733275, 2021). "Similar findings were noticed with bladder cancer repression through the action of the ALKBH5 and METTL3 in a reciprocal manner on integrin alpha-6 transcript, which enhances various cellular motility and signaling events." (PMID 33511112, 2020). "The ALKBH5 inhibits the translation of integrin alpha-6 in the m6A-dependent pathway and decreases bladder cancer adhesion, migration, and invasion." (PMID 33511112, 2020). "Overexpression of ALKBH5 in bladder cancer J82 cells and UM-UC-3 cells resulted in decreased CDCP1 protein level without changing its mRNA." (PMID 30796352, 2019). "ALKBH5 reduced CKα expression in an m6A-dependent manner, which significantly inhibited glucose uptake and lactate production by bladder cancer cells, and reduced intracellular ATP levels, increasing the sensitivity of bladder cancer to chemotherapy." (PMID 40610445, 2025). "Furthermore, in bladder cancer cells, ALKBH5 knockdown promotes bladder cancer cell migration via CK2‐mediated glycolysis." (PMID 38572667, 2024). "Nonetheless, recent reports show that ALKBH5 plays an inhibitory role in bladder cancer." (PMID 39011034, 2024). "Additionally, the downregulation of ALKBH5 expression promotes bladder cancer cell proliferation, migration, and invasion, resulting in reduced sensitivity to cisplatin chemotherapy." (PMID 39759516, 2024).
bladder cancer (continued). "Research has reported that ALKBH5 was downregulated in bladder cancer cells." (PMID 37264402, 2023). "Moreover, ALKBH5 overexpression can enhance the sensitivity of bladder cancer cells to cisplatin through the CK2α-mediated m6A-dependent glycolysis pathway." (PMID 37264402, 2023). "However, in other studies, ALKBH5 was shown to be down-regulated as a tumor suppressor, such as in bladder cancer and PC." (PMID 37007161, 2023). "METTL14, YTHDC1, and WTAP may be protective factors for bladder cancer, the higher expressions were related to the longer overall survival of patients, while IGF2BP1-3, YTHDF1, LRPPRC, ALKBH5, and FTO were risk factors for bladder cancer." (PMID 37701836, 2023). "Knockdown of ALKBH5 promotes the proliferation and migration of bladder cancer cells, which may be achieved by increasing glucose utilization, lactate production and intracellular ATP levels in cancer cells." (PMID 37264402, 2023). "In bladder cancer, downregulation of ALKBH5 was positively correlated with patient survival." (PMID 37007161, 2023). "The overexpression of ALKBH5 could inhibit disease progression through the m6A-CK2a-mediated glycolytic pathway and increase the sensitivity of bladder cancer to cisplatin." (PMID 35024366, 2021). "Mechanistically, ALKBH5 further regulates the casein kinase 2 (CK2) α-mediated glycolysis pathway by mediating the stability of CK2α, ultimately inhibiting bladder cancer progression in an m6A-dependent manner and increasing cisplatin sensitivity." (PMID 39759516, 2024). "Altogether, our data identify METTL3/ALKBH5 and SLC3A2/SLC7A5 as the potential therapeutic targets and pave the way for future development of therapy for bladder cancer related to PAHs." (PMID 38267663, 2024). "For example, a lncRNA BLACAT3 underwent m6A modification mediated by ALKBH5, leading to the stabilization of BLACAT3 RNA structure and thereby promoting angiogenesis in bladder cancer." (PMID 38351022, 2024). "In the bioinformatic analysis of the GEO database, we detected that both the ALKBH5 and FTO genes were connected with bladder cancer." (PMID 33634966, 2021). "In bladder cancer cells, METTL3 and ALKBH5 alter cell adhesion through the m6A methylations of the ITGA6 mRNA 3’UTR20." (PMID 31959747, 2020). "For example, in bladder cancer tumorigenesis, m6A methyltransferase METTL3 and demethylases ALKBH5 mediate the m6A modification in 3’-UTR of CDCP1 mRNA." (PMID 33099572, 2020). "Yang et al34 showed that METTL3 and ALKBH5 regulated m6A modification of the 3′‐UTR of the oncogene CDCP1 mRNA and that YTHDF1 recognized m6A modification to promote CDCP1 translation in bladder cancer." (PMID 32808488, 2020). "In bladder cancer (BLCA), NSUN2, IGF2BP2, YTHDC1, ALKBH5, TRDMT1, and ZC3H13 were identified, with NSUN2—a 5-methylcytosine (m5C) writer—previously shown to promote tumorigenesis and cancer stemness by stabilizing CCND1 mRNA and driving epithelial–mesenchymal transition." (PMID 40565233, 2025). "During the malignant transformation, dysregulation of METTL3/ALKBH5 induced the up-regulation of m6A levels on SLC3A2/SLC7A5 mRNA in cells, which promoted translation and expression of SLC3A2/SLC7A5, and thus accelerated bladder cancer growth and metastasis." (PMID 38267663, 2024). "Our data suggests that targeting METTL3/ALKBH5 and their downstream genes SLC3A2/SLC7A5 may be a potential therapeutic strategy for bladder cancer." (PMID 38267663, 2024). "Specifically, only the FTO gene, and not the ALKBH5 gene, was highly overexpressed in the tissue of bladder cancer." (PMID 33634966, 2021). "It has been demonstrated that in bladder cancer, especially in patients with poor prognosis, the overall abundance of m6A in tumor tissues is significantly increased and the expression levels of m6A-related regulators METTL3 and ALKBH5 are significantly abnormal." (PMID 38267663, 2024).
bladder cancer (continued). "Similarly, Jin et al35 found that METTL3 and ALKBH5 regulated the m6A modification of the 3′‐UTR of the oncogene ITGA6 mRNA and that YTHDF1/3 recognized m6A modification to promote ITGA6 translation in bladder cancer." (PMID 32808488, 2020).
acute myeloid leukemia (37 papers, 2021 to 2026). Acute myeloid leukemia (AML) is a group of neoplasms arising from precursor cells committed to the myeloid cell-line differentiation. "Core components of the m6A machinery, including METTL3, METTL14, FTO, and ALKBH5, have been implicated in acute myeloid leukemia (AML) pathogenesis." (PMID 40973767, 2025). "In addition, ALKBH5 functions as a Pivotal independent prognostic marker in acute myeloid leukemia, with its overexpression associating with unfavorable clinical Outcomes and persistence of leukemia stem cells, thereby implicating its role in therapeutic resistance and disease progression." (PMID 40986143, 2025). "Functional annotations in acute myeloid leukemia (AML) revealed RMPs such as ALKBH5 as critical mediators of m6A dynamics, influencing pathways involved in translation initiation, immune regulation, and tumorigenesis." (PMID 41672979, 2026). "A study on acute myeloid leukemia (AML) has shown that ALKBH5 regulated the expression of TACC3 (a transcription factor) in an m6A-dependent manner, which critically influenced leukemic cell transformation and AML development." (PMID 40001461, 2025). "The transcription factor 15 (TCF15), which is specifically expressed in leukemia stem cells, is responsible for the dysregulated expression of ALKBH5 in acute myeloid leukemia." (PMID 40986143, 2025). "Alkbh5 has been shown to be necessary for maintaining acute myeloid leukemia stem cell function but is expendable in normal hematogenesis." (PMID 37588656, 2023). "The mutations of m6A regulatory genes, METTL3, METTL14, YTHDF1, YTHDF2, FTO, and ALKBH5, have been identified in acute lymphoblastic leukemia, multiple myeloma, and acute myeloid leukemia (AML)." (PMID 33898522, 2021). "Mechanistically, ALKBH5 may exert pro-tumorigenic activities on acute myeloid leukemia via the posttranscriptional regulation of its critical targets." (PMID 40986143, 2025). "In addition, ALKBH5 is essential for the initiation and progression of acute myeloid leukemia and the stemness maintenance of leukemia stem cells, yet it is dispensable for normal hematopoiesis." (PMID 40986143, 2025). "Moreover, ALKBH5-dependent m6A demethylation of the TACC3 transcript is frequently modified in acute myeloid leukemia (AML), resulting in CSC stemness maintenance." (PMID 37853437, 2023). "Our data indicate that BP can inhibit acute myeloid leukemia cell proliferation by downregulating ALKBH5-mediated m6A demethylation of EIF4EBP1 and MLST8 mRNAs, which may have potential to prevent and treat this disease." (PMID 35579750, 2022). "ALKBH5 is frequently overexpressed in acute myeloid leukemia (AML), which correlates with poor prognosis in AML patients." (PMID 40271153, 2025). "An illustrative example is the abnormal overexpression of ALKBH5 in acute myeloid leukemia (AML), which serves as a prognostic indicator for poor outcomes and plays a pivotal role in the self-renewal of cancer stem cells." (PMID 37546413, 2023). "Potential drugs such as CS1, CS2, and NSC48890, suggested for acute myeloid leukemia, and imidazobenzoxazin-5-thione (MV1035) aiming for tumor immunity target the inhibition of FTO and ALKBH5, respectively." (PMID 39629934, 2025). "High METTL3, WTAP, FTO, ALKBH5, and YTHDF2 expression has been observed in all subtypes of acute myelogenous leukaemia (AML), and high WTAP, ALKBH5 and IGF2BP1 expression are related to the poor prognosis of AML patients." (PMID 35518355, 2022). "In acute myeloid leukemia (AML), ALKBH5 was positively regulated by KDM4C and the high level of ALKBH5 increased the stability of AXL (AXL receptor tyrosine kinase), thus promoting leukemia stem cells." (PMID 36686788, 2022). "In acute myeloid leukemia (AML), ALKBH5 was required to maintain leukemia stem cell self-renewal and promote AML tumorigenesis by regulating the expression of a set of critical genes (AXL and TACC3) at the posttranscriptional level." (PMID 34759347, 2022).
acute myeloid leukemia (continued). "In acute myeloid leukemia (AML), abnormal expression of m6A regulatory factors, including METL3, METTL14, FTO, ALKBH5, and IGF2BP1/2/3, can regulate the expression of MYC." (PMID 33926508, 2021). "However, in acute myeloid leukemia (AML), TACC3 exerts pro-cancer effects via ALKBH5-catalyzed demethylation." (PMID 36830673, 2023). "Here, we set out to investigate the potential of the BP-regulated ALKBH5/MLST8/EIF4EBP1 axis on prevention and treatment of acute myeloid leukemia (AML)." (PMID 35579750, 2022). "We hypothesized that FTO and ALKBH5 play crucial proleukemogenic roles in T-ALL, akin to their functions in acute myeloid leukemia (AML)." (PMID 40435251, 2025). "In addition, ALKBH5 is known to post-transcriptionally regulate TACC3 to promote tumorigenesis and cancer stem cell self-renewal in acute myeloid leukemia (AML), whereas the KDM4C-ALKBH5-AXL signaling axis participates in chromatin alterations in AML leukemia stem cells." (PMID 34491904, 2021).
leukemia (35 papers, 2019 to 2025). A malignant (clonal) hematologic disorder, involving hematopoietic stem cells and characterized by the presence of primitive or atypical myeloid or lymphoid cells in the bone marrow and the blood. "Hematoxylin and eosin (H&E) and immunohistochemical staining of proliferating cell nuclear antigen (PCNA) further demonstrated that deficiency of Fto instead of Alkbh5 restrained leukemia cells infiltration and proliferation." (PMID 40435251, 2025). "We here show that Alkbh5-deficient Mll-AF9 leukemia cells are also affected by the defects in the energy metabolism pathway." (PMID 37742191, 2023). "A previous study revealed that the RNA demethylase ALKBH5 was selectively activated in cancer stem cells and promoted tumorigenesis in leukemia; therefore, we tested whether our m6A score was associated with cancer stem cells in PCa." (PMID 36011028, 2022). "Alternatively, ALKBH5 knockdown can significantly increase the proportion of apoptotic AML cells and leukemia stem cells, suggesting that ALKBH5 silencing also promotes cell apoptosis." (PMID 40001461, 2025). "Our study uncovers a mechanism whereby the RNA m6A demethylase ALKBH5 regulates the stability of metabolic enzyme transcripts, thereby controlling energy metabolism in hematopoiesis and leukemia." (PMID 37742191, 2023). "To confirm that the ALKBH5-OGDH axis at least in part limits leukemogenesis in Mll-AF9 leukemia, we transfected MA9-WT cells with Ogdh or control siRNA." (PMID 37742191, 2023). "Previous studies have shown that Alkbh5 is required for maintaining the function of leukemia stem cells but is dispensable for normal hematopoiesis." (PMID 37588656, 2023). "Collectively, with a minor influence on normal hematopoiesis, ALKBH5 is considered as a crucial therapeutic target for leukemia." (PMID 35999621, 2022). "ALKBH5 also plays a key role in promoting the occurrence of leukemia by regulating the activity of key targets (such as TACC3 and USP1)." (PMID 35945641, 2022). "Small-molecule inhibitors of METTL3, FTO, ALKBH5 have recently been identified and have exhibited considerable anti-leukemia effects both in vitro and in mouse models." (PMID 35999621, 2022). "Further investigation confirmed MYB silencing markedly decreased ALKBH5 mRNA and protein amounts in leukemia cells." (PMID 35063010, 2022). "Recent works from our group and Dr. Chen’s group simultaneously revealed the key and selective role of ALKBH5 in self-renewal and maintenance of leukemia stem cells." (PMID 34485297, 2021). "The relevant experiments on leukaemia xenograft mouse model further potentiate the involvement of ALKBH5 in self-renewal and maintenance of AML-cells." (PMID 34207299, 2021). "For instance, increased expression of several m6A modifiers such as METTL3, FTO, and ALKBH5 have been observed in leukemia cells (discussed in the following)." (PMID 34485297, 2021). "Unexpectedly, the deficiency of Alkbh5 did not suppress the peripheral production of GFP+ leukemia cells." (PMID 40435251, 2025). "Combination of ALKBH5 inhibition with drugs targeting other metabolic pathways could be leveraged in the treatment of leukemia." (PMID 37742191, 2023). "In our MA9 leukemia mouse model, loss of ALKBH5 does not fully eliminate leukemia cells but does slow the progression of leukemia." (PMID 37742191, 2023). "In leukemia-initiating cells, the promoter regions of ALKBH5 have markedly elevated amounts of active histone markers, including H3K9ac, H3K4me3, H3K4me2 and H3K79me2, and reduced levels of the repressive histone marker H3K27me3 and H3K9me3, leading to a higher degree of chromatin openness." (PMID 35063010, 2022). "FTO and ALKBH5 are also involved in the occurrence and promotion of leukemia." (PMID 35945641, 2022). "In addition, ALKBH5 knockdown significantly promotes differentiation, blocks cell growth, induces apoptosis, reduces clonogenic ability in vitro and delays leukemia progression in vivo." (PMID 34001273, 2021).